ATR (ATR checkpoint kinase)
Diseases named in the same sentence as ATR in open-access papers (continued):
Sharing a sentence is not in itself a finding about the gene and the disease.
tumor (continued). "However, mice treated with both 673A and an ATM or ATR inhibitor had even greater reductions in tumor volume." (PMID 33664846, 2021). "Overall, the results generated here led to the development and optimization of a modified G2-assay using the VE-821 ATR inhibitor enabling time-efficient radiosensitivity assessments of cultured cells, and, potentially, of primary tumor cells obtained from biopsies." (PMID 34123995, 2021). "Taken together, these factors indicate that ATR inhibitors may sensitize tumor cells to DNA-damaging chemotherapies such as topoisomerase I inhibitors." (PMID 33513721, 2021). "Similar to Chk1, ATR also acts as a haploinsufficient tumor suppressor." (PMID 33556369, 2021). "As FOXM1 is a phosphorylation target of ATR, we also investigated pFOXM1 in treated tumours." (PMID 34819497, 2021). "Moreover, ATR inhibition in combination with RT has been shown to modulate the immune tumor microenvironment, leading to immunologic memory and lasting antitumor immunity." (PMID 33546122, 2021). "However, with the deepening of the research, the researchers found that the ATR-CHKl axis and CHKl protein kinase promote the growth of tumor cells." (PMID 34168220, 2021). "Besides DDR, ATM and ATR involve in cellular homeostasis, immune regulation, senescence, tumorigenesis and tumor progression." (PMID 34483751, 2021). "Another HRR-related gene is ATR, and alterations in this gene were seen in two tumours." (PMID 34680387, 2021). "Similarly, in germ cell tumors, ARID1A deficiency produced by CRISPR/Cas9 gene editing or pharmacological inhibition considerably sensitized tumor cells towards ATR inhibition." (PMID 34737943, 2021). "Therefore, when DNA-damaging stimulus affects DNA, simultaneous ATR inhibition leads to the accumulation of DNA single-strand breaks (SSBs) and DSBs, and, ultimately, the induction of tumor cell apoptosis." (PMID 33513721, 2021). "Hence, therapeutic inhibition targeting ATR has been shown to increase selective killing of tumor cells." (PMID 34930377, 2021). "PDX tumor growth was delayed in the ATR treatment group compared with the vehicle group." (PMID 33407601, 2021). "Finally, we observed enhanced synergistic tumor cell killing in ATRX KO cells with ATR and PARP inhibition, which is commonly seen in HR-defective cells." (PMID 34118569, 2021). "ATM and ATR signaling is deeply involved in multiple processes in tumor biology." (PMID 34483751, 2021). "Moreover, several studies have revealed that homozygous ATR deletion results in early-embryonic lethal effects, whereas reduction of ATR levels induces resistance to tumor development, as observed in ATR‐Seckel mice." (PMID 33672884, 2021). "Our results reveal a tumor suppressor role of SPOP in preventing DNA replication over-firing and genome instability and suggest that SPOP-mutated tumors may be susceptible to ATR inhibitor therapy." (PMID 34599168, 2021). "High TopBP1 expression may contribute to tumor development by reducing the strength of ATR/Chk1 activation." (PMID 33556369, 2021). "Given its characteristic immunogenicity, G1 cell cycle checkpoint deficiencies and associated sensitivity to DNA-damaging agents, we propose that MCC is a highly appealing tumor to test whether ATR inhibition can overcome resistance to PD-1 pathway blockade." (PMID 34298632, 2021). "Oncogene activation can impose replication stress on tumor cells, which may rely on ATR checkpoint function for survival." (PMID 34737943, 2021). "AZD6738, an ATR inhibitor, delayed tumor growth in a relevant PDX model." (PMID 33407601, 2021).
tumor (continued). "While admittedly our number of matched BBB and tumors is limited, the data from these specimens suggests that, later in oncogenesis, mutations in ATR pathway members, i.e., ATR and ETAA1, are being selected for as they observed in both the benign biopsy and its matched tumor." (PMID 32566745, 2020). "Furthermore, ATR inhibition downregulates PD-L1 expression in tumor cells by destabilizing PD-L1 in a proteasome-dependent manner and has resulted in enhanced immune cell killing." (PMID 33102516, 2020). "Additionally, the loss-of-function mutations re-sensitize different tumor types to various drugs, like EZH2-, PARP-, HDAC-, HSP90- or ATR-inhibitors." (PMID 32272809, 2020). "Furthermore, it has been suggested that with optimised dose scheduling, combined PARP and WEE1 or ATR inhibition can enhance tumour killing with minimal systemic toxicity, owing to higher basal levels of replication stress in malignant versus normal tissue." (PMID 32444694, 2020). "Combined treatment with olaparib plus ATR inhibition with VE821 induced cell death only in ATM-deficient A549 cells, suggesting that patients with ATM-deficient tumours could benefit from a combination of PARP and ATR inhibitors." (PMID 32183301, 2020). "Our studies thus identify a novel link between MYB and ATR in ACC that may have implications also for other types of neoplasms with activation of the MYB oncogene." (PMID 32001675, 2020). "However, how EBV-induced ATR activation promotes NPC by influencing inflammatory microenvironment, such as tumor-associated macrophages (TAMs), remains elusive." (PMID 32917854, 2020). "for deleterious ERCC4 variants, the effectiveness of cisplatin is expected for disrupting mutations; PARP inhibitors are selectively toxic to tumours with RAD51C mutations, and tumours with ATM mutations had a positive response to cisplatin, and inhibitors of PARP1, ATR and DNA-PKc." (PMID 32756499, 2020). "In addition, ATR inhibition attenuates irradiation-induced PD-L1 upregulation and decreases the number of tumor-infiltrating Tregs in mouse models." (PMID 33102516, 2020). "Similarly, we have recently shown that ATR downregulation activates BSFs and enhance their paracrine procarcinogenic effects both in vitro and ion orthotopic tumor xenografts." (PMID 32414408, 2020). "It is consistent with the hypothesis that in response to PARP inhibitor therapy or platinum chemotherapy, the tumor acquired a mechanism to activate HR despite retaining BRCA1 deficiency, which can then be blocked with ATR inhibition." (PMID 32568634, 2020). "Therefore, the proposed mechanism behind the synthetic lethal relationship between ATR and ATM is that ATR inhibition increases the number of DSBs and tumor-specific loss-of-function mutations in ATM impair the repair of these DSBs." (PMID 32731592, 2020). "At the transcriptomic level, tumours with high MYC mRNA and high ATR mRNA expression were also associated with higher tumour grade, high-risk Nottingham Prognostic Index (NPI), ER−, PR−, Genefu subtype (ER−/Her-2−), triple negative and PAM50.Basal phenotypes (all adjusted p values ≤ 0.01)." (PMID 30746633, 2019). "A total of 793 tumours were suitable for ATR and MYC protein co-expression analyses." (PMID 30746633, 2019). "Therefore, ATR overexpression in MYC overexpressed tumours will be expected to promote proliferation and aggressive phenotypes." (PMID 30746633, 2019). "In ER- tumours, MYC overexpressed tumours with high ATR protein levels had the worst survival." (PMID 30746633, 2019).
tumor (continued). "The tumor suppressor genes ATR and ATM, as well as their yeast homologs Mec1 and Tel1, prevent telomere fusions during pre-senescence by unknown mechanisms." (PMID 29879139, 2018). "Regarding tumor site, telomere length, ATR, ATM and Chk1 were shown to be altered." (PMID 29870526, 2018). "Tumor located in colon had higher expression of ATR than its adjacent mucosa." (PMID 29870526, 2018). "Through the application of tumor exome sequencing analysis, a patient-specific neoantigen derived from the mutant epitope of the ATR (ataxia telangiectasia and Rad3 related) gene product was identified to elicit a strong T-cell response following ipilimumab treatment." (PMID 28116322, 2017). "Most tumours showed high proliferation (Ki67 marker), variable oxidative DNA damage (8‐oxoguanine lesions) and formation of 53BP1 nuclear ‘bodies’, the latter indicating (along with ATR‐Chk1 signalling) endogenous replication stress." (PMID 28383788, 2017). "Since ATR demonstrated tumor growth inhibition and about 60% in vitro killing of tumor cells, tumor evasion might prove a challenge in later clinical translation." (PMID 27602488, 2016). "Due to the central role of ATR in the DDR, synthetic lethal interactions of ATR with certain tumor-mutated DNA-repair genes might at least partly explain this selective tumor cell killing by ATR-inhibitors." (PMID 26755646, 2016). "Besides the canonical phosphorylation of CHK1 by ATR, multiple other substrates are phosphorylated by ATR in various tumor identities." (PMID 26755646, 2016). "Additional ATR were generated with a 1:10 ratio of T cell:tumor cell binding complexes." (PMID 27602488, 2016). "Therefore, ATR inhibition in tumor cells can induce severe DNA damage, while normal cells with a functional G1 checkpoint are unaffected." (PMID 27246979, 2016). "Finally, ATR demonstrated significant tumor growth inhibition in vivo and prolonged overall survival." (PMID 27602488, 2016). "Oncogene-induced replication stress activates the ATR pathway in many neoplasias including lung." (PMID 26438152, 2015). "Similarly, ATR expression was also higher in tumor tissue compared to matched normal controls (p = 6.6 × 10−61)." (PMID 25880358, 2015). "ATR inhibitor would be an effective tumor radiosensitizer with carbon ion irradiation." (PMID 26286029, 2015). "Although the experiments presented here were performed only in one cell line, this study provides valuable information regarding complex ATR-mediated signaling changes, and should be further validated in other cell lines as well as in primary tumor samples from patients, which is our next goal." (PMID 25003641, 2014). "This in turn leads to ATR activation and tumor cell apoptosis." (PMID 25104095, 2014). "A broader impact of Ajuba and related molecules is that they could have oncogenic properties during early events of cellular transformation by inhibiting the protective or tumor suppressive effects of ATR." (PMID 23755068, 2013). "Furthermore, decreased survival and increased tumour incidence were recorded in the ATR+/- animals compared to their ATR+/+ counterparts." (PMID 19440510, 2008).
tumor (continued). "Moreover, our findings suggest that combined Src and ATR inhibition may result in more comprehensive tumor suppression." (PMID 41343245, 2026). "Beyond PARP inhibition, ATR inhibitors—such as ceralasertib and elimusertib—act by inducing replication fork collapse and accumulation of double-strand breaks during S-phase, which activates innate immune pathways and enhances tumor sensitivity to both radiotherapy and immunotherapy." (PMID 41373427, 2025). "Indeed, higher AEP levels in nonresponder patients correlated with reduced ATR nuclear levels in 9 out of 10 patients, further confirming our previous observations revealing a direct role for AEP in regulating the levels of ATR and reinforcing their connection with tumor resistance to radiotherapy." (PMID 40012043, 2025). "We hypothesized that the combination of oxaliplatin and the ATR inhibitor VE-822 (Vox thereafter) would offer greater tumor control and immunogenicity, favoring the establishment of a potent antitumor immune response and greater sensitivity to anti-PD-1 antibodies." (PMID 40139833, 2025). "Mechanistically, caffeine exerts anti-tumor activity by modulating key cellular pathways involved in carcinogenesis, including the inhibition of phosphodiesterases, antagonism of adenosine A2A receptors, and disruption of the DNA damage response through ATR-Chk1 pathway inhibition." (PMID 40650030, 2025). "Moreover, BLM emerges as a regulator of the tumor immune microenvironment, inducing MHC-I expression in a manner dependent on ataxia-telangiectasia mutated/ataxia telangiectasia and Rad3-related–NF-κB (ATM/ATR–NF-κB) signaling." (PMID 39106105, 2024). "Also, in tumors with high levels of microsatellite instability (MSI-H) that are characterized by decreased levels of WRN helicase, it has been shown that ATR inhibition may potentiate tumor cell death." (PMID 38474014, 2024). "Importantly, four genes (MET, ATRX, ATR, and BRCA2) associated with active clinical trials were mutated specifically in one region of the tumours investigated, suggesting that may have been missed if tumour heterogeneity had not been considered." (PMID 39766052, 2024). "Lee demonstrated that ATR inhibition showed better synthetic lethality and increased anti-tumour immunity in cells with mismatch repair deficiency and higher infiltrating CD8+ cells in the tumour, improving prognosis in tumours exhibiting high replication stress." (PMID 39140283, 2024). "Furthermore, in the attempt to discover acquired genetic vulnerabilities, we find that ATM but not ATR inhibition overcomes PARP inhibitor (PARPi) resistance in H2AX-deficient tumours by interfering with CtIP-mediated fork protection." (PMID 38789420, 2024). "Consequently, ATR inhibition can lead to unhindered cell cycle progression in cells harbouring DNA damage, resulting in mitosis of cells with damaged DNA, mitotic catastrophe, and tumour cell death." (PMID 38287179, 2024). "Furthermore, because cis-ATR has antiapoptotic properties, we surmise that it may have an oncogenic role, whereas Pin1 may have tumor-suppressive properties in relation to ATR’s anti-apoptotic activity at the mitochondria." (PMID 37511442, 2023). "Although early clinical studies investigating ATR inhibition in tumors harboring ATM mutations or lacking ATM protein expression have shown preliminary signals of anti-tumor activity, the optimal method for identifying ATM LOF in a broader population remains to be established." (PMID 37277454, 2023). "In addition to providing an explanation for the critical requirement of C16orf72 in cell viability when ATR activity is compromised 31, these observations also suggest ATRi may provide an effective treatment in tumours with elevated R-loops." (PMID 37591890, 2023). "Furthermore, we hypothesize that ATR inhibition results in anti-tumor activity in DDR alterations beyond ATM, such as BRCA1/2 and others." (PMID 37277454, 2023).
tumor (continued). "Thus, ATR inhibition has anti-tumor activity against preclinical ARMS models, which may be clinically translatable." (PMID 35879366, 2022). "Prompted by the finding that loss of E2F activity sensitizes cells to ATR inhibition, we examined whether the cytotoxic effect exhibited by the combination of E2Fi and ATRi could be recapitulated in vivo, by assessing PC3 tumor growth in nude mice treated with these drugs." (PMID 36230876, 2022). "Likewise, ATR inhibitors have been demonstrated to potentiate tumor immunity." (PMID 34572908, 2021). "Given that Cyclin C depleted cells had reduced basal levels of DNA:RNA hybrids, correlating with reduced ATRi/CHK1i-induced hybrid formation, it is possible that basal DNA:RNA hybrid levels could be used as a phenotypic biomarker in patient tumour samples to predict ATR and CHK1 inhibitor efficacy." (PMID 34329458, 2021). "Interestingly, both WEE1 and ATR inhibitors were shown to affect anti-tumor immune responses after radiation, and simultaneous ATR/WEE1 inhibition together with radiotherapy could potentially be more beneficial in this aspect." (PMID 34359691, 2021). "Furthermore, ATR expression in CAFs was inversely correlated with tumor recurrence and progression." (PMID 32414408, 2020). "Nuclear PTEN negative/high ATR tumours were associated with the worst BCSS (p = 0.029)." (PMID 29396668, 2018). "Defects in ATM could also be compensated through the activity of ataxia telangiectasia And rad3-related protein (ATR), thus indicating potential synthetic lethality interactions between these pathways, as ATM mutated tumours would be vulnerable to ATR inhibition." (PMID 29329208, 2018). "Thus we could demonstrate that cognate ATR redirected 2C T cells in vivo to engrafted human CD19+ Raji cells resulting in redirectional tumor lysis." (PMID 27602488, 2016). "ATR deficiency was significantly associated with menopause (P = 0.025), strong expression of ATM (P = 0.017) and MRE11 (P = 0.040) with pre-menopausal SOC, strong expression of MRE11 (P = 0.016) with low tumor grade, and strong expression of BRCA1 (P = 0.015) with early clinical stage." (PMID 24752797, 2014). "To increase clinical relevance we analyzed published results of clinical trials and reported blood tumor barrier (BTB) penetration of the WEE1 inhibitor adavosertib and the ATM/ATR inhibitor BAY-1895344." (PMID 41585496, 2026). "Typical examples include combining the PARPi olaparib with the anti‐angiogenic antibody bevacizumab to enhance tumour sensitivity to PARP inhibition, and pairing PARPis with agents targeting other SL‐related genes, such as WEE1, ATR or CHK1 inhibitors." (PMID 41537447, 2026). "Multiple studies have shown that under selective pressure from PARP or ATR/CHK1 inhibitors, tumour cells can upregulate enzymes in the serine/glycine–folate cycle and de novo purine/pyrimidine synthesis, thereby increasing dNTP and NADPH supply." (PMID 41537447, 2026). "Compared to monotherapies, combining HER3-DXd with an ATR inhibitor enhanced DNA damage, sub-G1 arrest, apoptosis, downregulation of DDR and cell cycle regulatory proteins, and tumour growth inhibition." (PMID 41986659, 2026).